MCL1 (MCL1 apoptosis regulator, BCL2 family member)
Diseases named in the same sentence as MCL1 in open-access papers (continued):
Sharing a sentence is not in itself a finding about the gene and the disease.
cancer (continued). "In addition, the gene of MCL-1, which is a member of pro-apoptotic Bcl-2 family, was found to be the target of miR-519d in T-47D-cancer stem cells." (PMID 28423543, 2017). "As the MCL-1 is an important anti-apoptotic protein in cancers, we speculated that the miR-519d may promote the cisplatin-induced cell death by down-regulating the expression of MCL-1 in the T-47D-CSCs." (PMID 28423543, 2017). "Indeed, there is now an urgent need for specific and potent small molecule inhibitors of MCL-1 that efficiently target cancer cells while sparing physiological cellular functions of MCL-1." (PMID 28079887, 2017). "One of the most commonly amplified genes in human cancer, MCL-1, has been shown to be either amplified at the genomic level or over-expressed in a significant fraction of DLBCL patients, making it an important candidate for therapeutic targeting particularly in patients who fail on R-CHOP8,14." (PMID 29269870, 2017). "This study provides evidence that inhibition of Mcl-1 might be a common therapeutic method for treating cancers." (PMID 29383093, 2017). "Mcl-1 gene amplifications are frequently found in many types of cancer." (PMID 28516063, 2017). "In a broader scope beyond sunitinib, accumulating evidence reported compensatory activation of PI3K/AKT/mTOR signaling pathway and/or heightened Mcl-1 expression in diverse cancer types resistant to other TKIs including imatinib, dasatinib, erlotinib, and gefitinib." (PMID 29066973, 2017). "MCL-1 knockdown sensitizes cancer cells to aspirin-induced apoptosis." (PMID 26918349, 2016). "Moreover, several anti-apoptotic proteins, such as Bcl-2 and Mcl-1, which are known to be crucial for cancer cell survival, are direct target genes of STAT3 and NFкB." (PMID 27539371, 2016). "A growing body of cancer research evidence has indicated that activation of gp130/STAT3 induces the expression of multiple survival, proliferation and antiapoptosis associated genes, such as MCL-1, Bcl-2, Bcl-XL, Survivin and cyclin D1." (PMID 27537522, 2016). "Strategies to inhibit both mitochondrial and anti-apoptotic functions of Mcl-1 may synergize by restricting cancer cell proliferation and activating cell death." (PMID 27875574, 2016). "However, none of these compounds can bind and antagonize the prosurvival activity of the Mcl-1 Bcl-2 family member, which promote the development of many cancers and/or in their resistance to chemotherapy." (PMID 26959881, 2016). "Several past studies indicated that Mcl-1 is an important cancer target." (PMID 26921175, 2016). "Moreover, suppression of the Sirt3-mediated mitophagy promotes apoptotic cell death in the hypoxic cancer cells likely by enhancing the degradation of anti-apoptotic proteins Mcl-1 and survivin through a ROS-dependent proteasomal pathway." (PMID 27270321, 2016). "Accordingly, Mcl-1 targeting or depletion may sensitize cancer cells to radiation-induced apoptosis." (PMID 27513864, 2016). "Accordingly, studies will be undertaken that address whether targeting MUC1-C can also reverse MCL-1-mediated resistance to anti-cancer agents used for the treatment of TNBC8." (PMID 27217294, 2016). "Indeed, Mcl-1 is the current focus of widespread cancer drug development efforts, and a number of Mcl-1 inhibitors are in the cancer drug development pipeline worldwide." (PMID 26921175, 2016). "BCL2L1 and MCL1 are key anti‐apoptotic genes, and critical for cancer progression." (PMID 27264345, 2016). "However, several pathways modulate the apoptosis signaling and contribute to apoptosis resistance in cancers, such as Bcl-2 and Mcl-1 proteins, autophagy processes, aberrant nuclear export signaling, etc." (PMID 26923134, 2016).
cancer (continued). "The examples of Mcl‐1 inhibitors described here demonstrate that the “undruggable” challenge that PPIs present can be tackled effectively and is likely to lead to a novel inhibitors for the treatment of cancer." (PMID 26696548, 2016). "miR-15, miR-16, and miR-29 suppress MCL1 expression in human malignant tumor cells." (PMID 27356624, 2016). "Moreover, although there is considerable variation in Mcl-1 and Bcl-xL degradation kinetics between different cancer types, our dynamic modeling analysis showed that such variability mostly affects the timing to mitotic death, but not the extent." (PMID 27811996, 2016). "Variation in expression levels of Mcl-1 and Bcl-xL largely determine variability in sensitivity to mitotic death induced by anti-mitotics, such as paxlitaxel and Kinesin-5 inhibitor, across different cultured cancer cell lines." (PMID 27811996, 2016). "In parallel, since in different cancer cells Mcl-1 is induced by Akt and STAT-3 intracellular pathways, which are implicated in B-CLL pathogenesis, we have investigated the potential involvement of Akt and STAT-3 in the anti-leukemic activity of Met-DCA cocrystal." (PMID 26959881, 2016). "Moreover, ISG15 abolishes TNF-α-activated NF-κB signaling and decreases the transcription of NF-κB-modulated genes including XIAP and Mcl-1, two oncogenes in various cancers." (PMID 27659523, 2016). "However, recent studies suggest that cancer cells develop resistance to ABT-737 through the upregulation of Mcl-1, and in many instances this resistance can be overcome by the downregulation of Mcl-1." (PMID 26927133, 2016). "Therefore, strategies to interfere with Mcl-1 are currently explored such as the design of novel compounds that bind to Mcl-1 or the discovery of molecules that suppress Mcl-1 levels in cancer cells." (PMID 26474387, 2015). "Thus, FTY720 enables TRAIL-induced apoptosis through up-regulation of DR5 and down-regulation of Mcl-1 in human cancer cells." (PMID 25843953, 2015). "The cyto-protective effect of NF-κB could be mediated by its downstream targets that have anti-apoptotic effects or by cancer-related proteins, i.e. Mcl-1." (PMID 25875501, 2015). "Based on these results, specific CDK9 inhibitors and identification of a new Bay 61–3606 target for Mcl-1 degradation may be beneficial for the treatment of cancers in which Mcl-1 contributes to the development of resistance to anticancer therapeutics." (PMID 26720004, 2015). "Some reports have shown that the RNA interference of Mcl-1 could sensitize cancer cells to chemotherapy." (PMID 26457704, 2015). "In this way, loss of 4E-BP1 phosphorylation has previously been shown to result in a decrease of Mcl-1 protein expression in various cancer types in vitro and in vivo leading to therapeutic benefit and overexpression of eIF4E led to Mcl-1 expression in our models." (PMID 25627260, 2015). "NF-κB is a sequence specific transcription factor that regulates expression of many cellular genes such as genes involved in cancer cell survival (Mcl-1), proliferation (C-myc, Cyclin D1), and invasion (matrix metalloproteinase MMP-9), which play important roles in carcinogenesis." (PMID 25875501, 2015). "Not surprisingly, dysregulation of MCL-1 ubiquitylation and turn-over have been repeatedly associated with cancer and cancer chemoresistance." (PMID 25806049, 2015). "Possible mechanistic explanations for increased MCL1 expression may be an amplification of the MCL1 gene locus, as detected in other cancer types and cytokine and growth factor signaling resulting from tissue inflammation known to increase MCL1 expression." (PMID 25749045, 2015). "Hence, Mcl-1 has been identified as an important target in majority of human cancers and several therapeutic strategies focusing on Mcl-1 inhibition are currently under development." (PMID 26497853, 2015). "Future studies regarding the detailed mechanisms of Mcl-1 regulation via CDK9 may help to develop a new targeted therapeutic strategy for cancer." (PMID 26720004, 2015).
cancer (continued). "Although overexpression of Mcl-1 does not directly promote the proliferation of tumor cells, its ability to suppress apoptosis plays a key role for cancer cell to protect against the apoptosis-inducing effect caused by toxic factors." (PMID 26078955, 2015). "For example, Mcl-1 down-regulation sensitizes cancer cells to anticancer drugs." (PMID 25605256, 2015). "Other studies suggest that vincristine may reduce Mcl-1 expression and promote the death of cancer cells, complicating the interpretation of our findings." (PMID 25652880, 2015). "Usp9X modulates Mcl-1 levels and counteracts apoptosis in cancer cells." (PMID 26008975, 2015). "From a mechanistic point of view, we identified down-regulation of Usp9X as well as Bag3 followed by enhanced Mcl-1-degradation as one of the driving mechanisms subjacent to the profound anti-cancer activity inherent to a combined inhibition of ERK signaling and Bcl-2/Bcl-xL." (PMID 26474387, 2015). "Mcl-1 is a key factor in the resistance of a variety cancers to radiation and chemotherapy." (PMID 25605256, 2015). "As many tumors depend on Mcl-1 for chemoresistance, we investigated whether targeting cyclin E/Cdk2 could sensitize cancer cells to BH3 mimetics." (PMID 26219338, 2015). "The reduction of Mcl-1 expression leads to apoptosis in numerous cancer cells." (PMID 26063499, 2015). "Owing to its ability to inhibit multiple CDKs, dinaciclib could attenuate the expression levels of several short-lived proteins, such as MCL-1, which may in turn trigger the apoptotic cascade in several cancers." (PMID 26059440, 2015). "Thus, Mcl-1 which sequesters a significant pool of BAK in cancer cells seems to be the major determinant for the sensitization of TIC10/ONC201 to ABT263-mediated apoptosis." (PMID 26474387, 2015). "Moreover, suppression of mTORC1-dependent translation has been shown to reduce the levels of MCL-1 and sensitize various cancer cells, including ABT-199 resistant DLBCL, to BCL-2 antagonists." (PMID 26460954, 2015). "Finally, MCL1 is an important anti-apoptotic protein upregulated by ERK or AKT signaling in many cancers including CLL." (PMID 26517243, 2015). "Based on the evidence that cancer types with BCL2 and MCL1 amplification are more prone to inhibition of their encoded proteins, we hypothesized that cancers with a significant frequency of BCL2L1 amplification are more dependent on BCL-XL for survival." (PMID 26134786, 2015). "Although Mcl-1 has emerged as a significant cancer cell survival and therapy resistance factor across multiple cancer indications, it is now widely recognized that capturing the therapeutic benefit of Mcl-1 antagonism will likely rely on rational synthetic lethal strategies." (PMID 26231047, 2015). "Since this construct contains the three Bcl-2 homology (BH) sequence motifs which participate in forming a binding site for inhibitors of hMcl-1, it is deemed to be crucial for structure-based design of novel anti-cancer drugs blocking the Mcl1 related anti-apoptotic pathway." (PMID 24789074, 2014). "Notably, gene alterations around the locus of MCL1 on 1q21 have been identified as early as 1994, when it was discovered that 1q21 is duplicated or rearranged in many types of cancer." (PMID 26556430, 2014). "In addition, frequent Mcl-1 gene amplification was identified in lung, breast, neural and gastrointestinal cancers, through which cancer cells depend on the expression of this gene for survival." (PMID 24529193, 2014). "Given the clear clinical importance of MCL1 in CLL, we rationalized that targeted inhibition of cdk9 might prove to be a useful therapeutic strategy in CLL and other cancers in which MCL1 is over expressed." (PMID 24495868, 2014). "Overexpression of Mcl-1 has been reported in cancer, including in AML at relapse." (PMID 25006537, 2014).
cancer (continued). "Given the difference in apparent binding affinity, however, we hypothesized that in cancer cells overexpressing Bcl-2 proteins, especially those addicted to Mcl-1, Mcl-1/VDAC interactions would dominate." (PMID 25341036, 2014). "Hence, Mcl-1 plays an early role in response to signals directing either cell survival or cell death and has been shown to be up-regulated in numerous malignant tumors." (PMID 24789074, 2014). "Inhibition of transcriptional CDKs as an effective anti-cancer strategy has gained considerable attention following the observation that many types of cancer cells rely on the production of short-lived mitotic regulatory kinases and apoptosis regulators such as Mcl-1 for their survival." (PMID 25277198, 2014). "The restoration of MCL1 expression can counteract the effect of miR-107 on the cancer cells." (PMID 25386925, 2014). "A growing body of evidence suggests that three anti-apoptotic proteins, i.e., survivin, Mcl-1, and Bcl-2, may be directly related to drug resistance in cancer." (PMID 24586249, 2014). "The pivotal role Mcl-1 plays in protecting cancer cells from apoptosis is well documented." (PMID 24213561, 2014). "Taken together, TRAF6 regulates MCL-1 stability in diverse cancer cell lines." (PMID 25340740, 2014). "Thus, the pathways that are critical for regulating Mcl-1 expression have been employed to target Mcl-1 for cancer therapy." (PMID 24529193, 2014). "The observation that Mcl-1 binds more avidly to VDAC suggests that in cancer cells characterized by Mcl-1 overexpression, the Mcl-1/VDAC interaction could be a major determinant in remodeling mitochondrial physiology." (PMID 25341036, 2014). "In summary, our findings suggest that MCL1 copy number or the MCL1:BCL-xL mRNA ratio may provide a rational enrichment strategy for identifying cancer patients whose tumors are most likely to respond to dinaciclib." (PMID 25289887, 2014). "We investigated whether the inhibition of survivin, Bcl-2 and Mcl-1 by honokiol could sensitize MDR cancer cells to conventional chemotherapy such as palictaxel." (PMID 24586249, 2014). "Interestingly, the predominance of transcriptional regulation of Mcl-1 by CpG DNA resembles those observed in cancer cells upon ER stress." (PMID 24466313, 2014). "Taken together, cafestol may be effectively used to enhance ABT-737 sensitivity in cancer therapy via downregulation of Mcl-1 expression and upregulation of Bim expression." (PMID 25375379, 2014). "We next examined whether the resistance of cancer cells overexpressing Mcl-1 to ABT-737 could be overcome by co-treatment with well-known chemopreventive agents, including resveratrol, curcumin, or cafestol." (PMID 25375379, 2014). "MCL1 is an important antiapoptotic oncogene that is overexpressed in the majority of cancers." (PMID 26556430, 2014). "Overexpression of Mcl-1 has been observed in a variety of cancers." (PMID 25153862, 2014). "Depletion of Mcl-1 has been well proven to sensitize human HCC cancer cells to apoptosis." (PMID 23594563, 2013). "Therapeutics that specifically target cancers involving Mcl-1 overexpression may function to improve binding of ATG12 to Mcl-1." (PMID 23840208, 2013). "Therefore, anti-apoptotic strategies, such as concomitant inhibition of Bcl-xL and Mcl-1 are expected to play a potentially important role in the near future to overcome drug resistance in certain cancers." (PMID 24103422, 2013). "More importantly, MCL-1 is a pro-survival member of the Bcl-2 family, which has been studied intensively for the past decades owing to their importance in the regulation of apoptosis, tumorigenesis and cellular responses to anti-cancer therapy." (PMID 23750239, 2013). "Mcl-1 also protects cancer cells against cell death and is known to contribute to chemoresistance." (PMID 24025188, 2013). "Mcl-1 expression renders cancer cells resistant to the Bcl-2 antagonist ABT-737." (PMID 23431463, 2013).
cancer (continued). "In various cancers, Bcl-xL and Mcl-1 are frequently overexpressed, suggesting that resistance to apoptosis could imply these two key anti-apoptotic factors." (PMID 24103422, 2013). "Our findings identify miR-125b as a potent regulator of Mcl-1 and IL6R, which may provide a novel therapeutic strategy for treatment of HCC and other Mcl-1 or Il6R-driven cancers." (PMID 22942733, 2012). "Cumulating evidence indicates that HPV E6/E7 may regulate the expression of NOXA and MCL1 in different cancer cells." (PMID 22548841, 2012). "Abundant, dysregulated Mcl-1 expression is an important determinant of drug resistance in cancer." (PMID 23056582, 2012). "Upregulation of Mcl-1, as a consequence, could provide pivotal protection against apoptotic signals during dissemination and colonization when the majority of cancer cells remain under normoxia." (PMID 22276222, 2012). "ABT-737, a Bad-like BH3 mimetic which selectively bounds to Bcl-2, Bcl-XL and Bcl-w, is highlighted as a promising anti-cancer agent, meanwhile, its low affinity with Mcl-1 and high basal level of Mcl-1 expression in cancer cells is preventing it from being efficient as a single agent." (PMID 23284992, 2012). "One of these, MCL-1, has been widely described as contributing to resistance to ABT-737 which might suggest a poor response in patients with cancers that express levels of MCL-1." (PMID 22898329, 2012). "The high levels of ROS, Hif-1alpha and Mcl-1 strongly suggest that modified signaling in co-infected cells may, in addition, support pathologies like cancer development and neurodegeneration." (PMID 23077614, 2012). "These cells may thus provide a model for the many types of cancer cells that exhibit impaired Mcl-1 degradation through the GSK3-targeted pathway." (PMID 23056582, 2012). "Mcl-1 also represents a survival factor for human cancer cells." (PMID 22179587, 2012). "Our current research suggests that USP9X regulates Mcl-1 expression in cancer cells." (PMID 23171055, 2012). "We found that effect modification of the NOXA and MCL1 SNPs on risk of HPV-associated cancers was evident for oropharyngeal but not for SCCHN at non-oropharyngeal sites." (PMID 22548841, 2012). "Pro-survival genes such as BCL-2 and MCL-1 have been observed to be redundantly regulated by multiple miRNAs in cancer; inappropriate silencing of these molecules by miRNAs in AD could exacerbate neurodegeneration." (PMID 23335942, 2012). "In the present follow-up studies in BL41-3 cells, Mcl-1 degradation was found to be independent of the GSK3-mediated pathway, providing a parallel to emerging findings showing that Mcl-1 degradation through this pathway is lost in many different types of cancer." (PMID 23056582, 2012). "Understanding these mechanisms may also provide further opportunities for affecting Mcl-1 splicing, translation and stability, and therefore ways of inducing apoptosis in cancer cells." (PMID 23284704, 2012). "Such information could be important for designing new ways to induce apoptosis in cancer cells in which abnormal Mcl-1 expression underpins pathology." (PMID 23024798, 2012). "Furthermore, our analyses revealed that USP9X expression correlates with that of Mcl-1 in human cancer tissue samples." (PMID 23171055, 2012). "In terms of patient cancers in which GSK3-mediated Mcl-1 degradation is inactive, it remains to be determined whether the presence of ERK activation/Thr 163 phosphorylation contributes to resistance upon prolonged drug exposure." (PMID 23056582, 2012). "Therefore, our data suggest that high susceptibility to TRAIL of metastatic cancer cells is associated with up-regulation of DR5 and concurrent down-regulation of c-FLIPL/S and Mcl-1." (PMID 21513580, 2011). "Taken together, we propose the following model for 2DG-ABT induced apoptosis in cancer cells: 2DG induces changes in Bak or Mcl-1 so that they can no longer associate." (PMID 21949692, 2011).